APOC3 (apolipoprotein C3)
Diseases named in the same sentence as APOC3 in open-access papers (continued):
Sharing a sentence is not in itself a finding about the gene and the disease.
hypertriglyceridemia (continued). "Reduced ABCA1 activity, as observed in T2DM, limits cholesterol transport from cells to small HDL particles, contributing to hypertriglyceridemia even at low plasma APOC3 levels, emphasizing the importance of ABCA1 in lipoprotein metabolism and cardiovascular health." (PMID 39684468, 2024). "Clinical trials have also delved into targeting APOC3 for treating hypertriglyceridemia." (PMID 39286687, 2024). "A recent study showed that APOC3 transgenic mice exhibit hypertriglyceridemia." (PMID 37304843, 2023). "In the hypertriglyceridemia cohorts, both APOC3 and triglyceride levels were significantly reduced." (PMID 38203499, 2023). "In addition, the increased mRNA levels of Apoc3, which is usually downregulated by insulin, reasserts some degree of IR in the liver contributing to hypertriglyceridemia by the diminished TG hydrolysis by the LPL." (PMID 34202724, 2021). "And supports the strong association of promoter region polymorphism in apolipoprotein C3 (APOC3) (rs2854117 [− 482C>T] and rs2854116 [− 455T > C]) found to be strongly associated with NAFLD and its associated diseases, hypertriglyceridemia, metabolic syndrome, and coronary artery disease." (PMID 32280452, 2020). "Together, these studies strongly suggest that APOC3 inhibition could be effective in treating hypertriglyceridemia and preventing atherosclerotic CVD, especially in conditions in which APOC3 levels are increased." (PMID 32849290, 2020). "Thus, suppression of hepatic APOC3 expression has become an interesting novel treatment for reducing hypertriglyceridemia and accumulation of atherogenic remnant particles." (PMID 32849270, 2020). "We chose two mouse hypertriglyceridemia models to mimic different hypertriglyceridemia subtypes in this study, including glycosylphosphatidylinositol-anchored high-density lipoprotein binding protein 1 knockout (Gpihbp1−/−) and apolipoprotein C3 transgenic (ApoC3-tg) mice." (PMID 31570698, 2019). "Because the two hypertriglyceridemia mouse models, namely, Gpihbp1−/− and ApoC3-tg mice, are generated by different genetic modifications, their TRLs may be different when representing the two types of hypertriglyceridemia." (PMID 31570698, 2019). "Therefore, Gpihbp1−/− and ApoC3-tg mice are obviously two different types of hypertriglyceridemia models with different TRL types." (PMID 31570698, 2019). "Specially, PCSK9 was associated significantly with hypercholesterolemia or combined hyperlipidemia; apoC3 was significant in hypertriglyceridemia, hypercholesterolemia, and combined hyperlipidemia; and sdLDL-C was highlighted in all current dyslipidemias classification." (PMID 27713142, 2017). "Another study indicated that the overexpression of APOC3 can lead to hypertriglyceridemia in vivo." (PMID 27843478, 2016). "A prospective case–control study involving 300 NAFLD patients and 300 healthy controls indicated that APOC3 rs2854116 genetic variations involved in the susceptibility to develop NAFLD, IR, hypertriglyceridemia, and low HDL in the Southern Chinese Han population." (PMID 26965314, 2016). "Apolipoprotein C3 (APOC3) is a component of triglyceride-rich lipoproteins, and APOC3 rs2854116 and rs2854117 polymorphisms have been associated with non-alcoholic fatty liver disease, hypertriglyceridaemia, and insulin-resistance." (PMID 21663607, 2011). "Recently, it has been proposed that two sequence variants in the promoter of the gene encoding human apolipoprotein C3 (APOC3, rs2854116 and rs2854117) were associated with hypertriglyceridaemia, nonalcoholic fatty liver disease and insulin resistance in lean individuals of South Asian descent." (PMID 21663607, 2011). "Since Novel-3 is non-coding and unable to produce a protein, its increased expression could lower functional APOC3 levels, providing a potential therapeutic strategy for conditions like hypertriglyceridemia, where reducing APOC3 expression has been shown to be advantageous." (PMID 40282372, 2025).
hypertriglyceridemia (continued). "APOC3 and ANGPTL3 inhibitors provide potent triglyceride reduction in monogenic and refractory forms, while metabolic agents such as GLP-1 receptor agonists target the hepatic and insulin-resistant components characteristic of polygenic or MASLD-associated hypertriglyceridemia." (PMID 41300829, 2025). "HNF4A also activated APOC3, which may contribute to hypertriglyceridemia." (PMID 35925965, 2022). "Apolipoprotein C-III (apoC3) and angiopoietin-like protein 8 (ANGPTL8), recognized as inhibitors of lipoprotein lipase, play a role in modulating hypertriglyceridemia." (PMID 39944202, 2025). "ApoC3 is an inhibitor for LPL-mediated lipolysis, and increases in apoC3 activity contribute to the development of hyperglyceridemia." (PMID 39234305, 2024). "In transgenic mice that overexpress human APOC3, the resulting elevation of TRLs such as VLDL induces hypertriglyceridemia, closely mirroring the dyslipidemia observed in humans and its associated cardiovascular risks due to TG accumulation in the bloodstream." (PMID 39684468, 2024). "Because APOC3 is an LPL inhibitor, the insulin-independent upregulation of APOC3 inhibits LPL, which reduces the hydrolysis of chylomicron, leading to hypertriglyceridemia." (PMID 37304843, 2023). "Multiple regression analysis indicated that low LPL, high ApoC2, high ApoC3, high ApoE, and high ANGPTL8 levels were the determinants of fasting hypertriglyceridemia." (PMID 34293055, 2021). "As a main component of triacylglycerol-rich lipoprotein (TRL) and high-density lipoprotein (HDL), ApoC3 plays an important role in the regulation of lipid metabolism and can regulate the decomposition and metabolism of TRL in hypertriglyceridemia." (PMID 29132372, 2017). "High concentrations of APOC3 are correlated with hypertriglyceridemia but no role during bacterial infection is known." (PMID 41326716, 2026). "Search terms included “olezarsen,” “IONIS-APOCIII-LRx,” “APOC3-LRx,” “Tryngolza,” “apolipoprotein C-III,” “APOC3,” “familial chylomicronemia syndrome,” “severe hypertriglyceridemia,” “volanesorsen,” and “plozasiran” or “ARO-APOC3,” combined using Boolean operators (AND/OR)." (PMID 41393714, 2025). "Given the relationship between hypertriglyceridemia and CVD risk, it is not surprising that loss of function mutations in ApoC3 confer protection against the risk of ischemic vascular disease and atherosclerotic plaque development." (PMID 40981413, 2025). "In a phase I study, ARO-APOC3 demonstrated safety and consistent reductions in APOC3, TG, and non-HDL-C, regardless of the underlying genetic cause of severe hypertriglyceridemia." (PMID 38291757, 2024). "APOC3 inhibition has received much interest as a potential CVD treatment approach for adults with and without diabetes with mild-to-moderate hypertriglyceridemia and increased CVD risk." (PMID 37972731, 2024). "While APOC3-overexpressing transgenic mice develop hypertriglyceridemia, this condition alone does not induce β-cell dysfunction or disrupt glucose homeostasis." (PMID 39684468, 2024). "Early studies in APOC3 transgenic mice concluded that the hypertriglyceridemia in those mice is not due to increased hepatic TRL APOB production or decreased lipolysis by LPL but rather results primarily from decreased tissue uptake of TRLs from circulation." (PMID 37972731, 2024). "Weight loss acquired via caloric restriction, pharmacological measures, or bariatric surgery improves hypertriglyceridaemia via multifaceted approaches including improved insulin resistance, glycaemic control, increase in LPL activity, and reduction in ApoC3 levels." (PMID 37233662, 2023). "Volanesorsen can be considered in the treatment of patients with severe hypertriglyceridemia or FCS to lower their elevated TG and apoC3 levels, prevent acute pancreatitis recurrence and improve their symptoms, thus facilitating their professional, social, and personal life." (PMID 35207255, 2022).
hypertriglyceridemia (continued). "The optical density was positively associated with the triglyceride concentration in the plasma from both hypertriglyceridemia mice models, while the turbidity (shown as OD650/triglyceride) of the Gpihbp1−/− mice plasma was significantly higher than the ApoC3-tg mice plasma." (PMID 31570698, 2019). "Moreover, APOC3 boosts VLDL secretion from the liver, worsening hypertriglyceridemia." (PMID 39286687, 2024). "Moreover, poloxamer 407 treatment in ApoC3-tg mice further increased triglyceride levels, but did not to induce large areas of pancreatic necrosis in this type of hypertriglyceridemia." (PMID 31570698, 2019). "The high concentration of ApoC3 in serum might lead to lipoprotein disorders and some vascular diseases such as atherosclerosis and hypertriglyceridemia; the relationship between ApoC3 and longevity is not clear yet." (PMID 26682220, 2015). "We observed that lowering APOC3 in Ai-DKO mice leads to downregulation of the expression of lipogenic genes in the liver and partially reverses the hypertriglyceridemia, but it does not affect hyperglycemia or hyperinsulinemia." (PMID 35964946, 2022). "Although hypertriglyceridemia contributes to CVD, it does not independently precipitate β-cell dysfunction, highlighting the complex metabolic interplay and the therapeutic potential of APOC3 as a target in managing CVD risks and metabolic disorders." (PMID 39684468, 2024).
atherosclerosis (105 papers, 2011 to 2025). A disease characterized by the build-up of fatty material and calcium deposition in the arterial wall resulting in partial or complete occlusion of the arterial lumen. "Genetic studies have shown that loss-of-function mutations in the APOC3 gene are associated with significantly lower triglyceride levels, reduced remnant cholesterol, and less coronary artery calcification, a marker of atherosclerosis." (PMID 40282372, 2025). "For instance, increased PCSK9 gene expression promotes the generation of LDL, while elevated APOC3 gene expression inhibits TG metabolism, both abnormal expressions predispose individuals to atherosclerosis, a significant contributor to myocardial infarction." (PMID 39960900, 2025). "We identified 447 individuals harboring a protective variant against atherosclerosis, including 422 heterozygous individuals and 13 homozygous for the APOC3 p.Arg19* variant." (PMID 39928272, 2025). "High expression of APOC3 is an independent risk factor for some diseases such as cardiovascular disease, atherosclerosis, and nonalcoholic fatty liver disease." (PMID 39928771, 2025). "Elevated APOC3 levels contribute to higher plasma triglycerides and increased risk of atherosclerosis, making APOC3 expression an attractive and logical therapeutic target." (PMID 40282372, 2025). "APOC3 is increasingly recognized as a key factor associated with atherosclerosis despite its presence in LDL in small amounts." (PMID 39684468, 2024). "The authors put hamsters on a high-cholesterol/high-fat diet to assessthe association between APOC3 and atherosclerosis and observed reducedlevels of TG, total cholesterol, ApoB, and ApoE and enhancedlevels of HDL-C and ApoA1." (PMID 39228490, 2024). "APOC3 plays a key role in the progression of atherosclerosis by increasing the risk of ischemic stroke and counteracting the effects of ApoC3, which can substantially reduce the size of atherosclerotic lesions." (PMID 36959823, 2023). "A direct association of apoCIII with atherosclerosis was revealed by clinical genetic studies and studies showing that loss-of-function mutations in APOC3 are associated with low TG levels and a reduced incidence of ischemic CVD." (PMID 36267630, 2022). "Genetic studies provide strong evidence linking variation in the APOC3 gene that encodes apoC-III with altered plasma triglyceride (TG) levels and risk of atherosclerosis." (PMID 36040803, 2022). "In that study, ApoC3 was considered a risk factor for the progression of atherosclerosis in patients with RA." (PMID 35637531, 2022). "APOC3 deficiency can delay the formation of atherosclerosis-induced HFD in rabbits, indicating this is a novel therapeutic target to treat atherosclerosis." (PMID 34922545, 2021). "We designed our exon 2-anchored CRISPR/Cas9 system to generate APOC3-KO rabbits with biallelic mutations to study the relationship between APOC3 deficiency, abnormal lipid metabolism, and the formation and development of atherosclerosis in this study." (PMID 34922545, 2021). "Insulin deficiency or resistance results in unrestrained ApoC3 expression and impaired triglyceride metabolism in the pathogenesis of atherosclerosis and hypertriglyceridemia." (PMID 31936903, 2020). "Nr1d2 also represses the expression of hepatic Apoc3 mRNA, a risk factor for atherosclerosis, and hepatic Insig1 overexpression reduces lipogenesis via decreased expression of Srebp1c mRNA and its target enzymes." (PMID 30423963, 2018).
atherosclerosis (continued). "The association of the S2 allele of the SstI polymorphism in the apoC3 gene with plasma apoCIII levels interacts with unfavorable lipid profiles to contribute to the development of atherosclerosis in the Li population in China." (PMID 29162127, 2017). "According to the results, the S1S2 and S2S2 apoC3 genotypes were associated with a 2-fold increase in the risk of atherosclerosis, indicating that the S2 allele contributes to susceptibility to atherosclerosis." (PMID 29162127, 2017). "Additionally, the presence of a loss-of-function mutation in the PCSK9 gene or the null mutation R19* in APOC3 was related to a low risk of atherosclerosis." (PMID 40440483, 2025). "Interestingly, in a hamster model, apoC3 deficiency exacerbated diet-induced atherosclerosis, though it improved hepatic steatosis in females." (PMID 41002378, 2025). "In a study, coronary artery calcification in type 1 diabetes, insulin deficiency was found to increase the level of APOC3, accelerate the formation of macrophage foam cells, and contribute to atherosclerosis; therefore, the expression of APOC3 can predict the risk of CVD in T1DM." (PMID 39684468, 2024). "A strong correlation exists between circulating proprotein convertase subtilisin/kexin type 9 and inflammation markers PTX3 and APOC3, which may be the cause of atherosclerosis in T2DM." (PMID 39684468, 2024). "These knockout models show a favorable cardiovascular profile, marked by fewer arterial plaques and reduced atherosclerosis risk—findings that parallel human studies showing that loss-of-function APOC3 mutations are associated with lower TG levels and reduced cardiovascular risk." (PMID 39684468, 2024). "Finally, we demonstrate, similar to a model of type 1 diabetes, that silencing APOC3 reduces atherosclerosis associated with diabetes, even in the presence of kidney disease." (PMID 38743496, 2024). "Furthermore, mechanistic studies in a mouse model of T1D indicate a causal role for APOC3 in diabetes-accelerated atherosclerosis." (PMID 33554869, 2021). "The SstI polymorphism in the apoC3 gene was also shown to influence the risk of atherosclerosis." (PMID 29162127, 2017). "Furthermore, reduced levels of APOC3 suppressed atherosclerosis associated with diabetes." (PMID 38743496, 2024). "Given the association between elevated APOC3, dyslipidemia, and heightened cardiovascular event risk, exercise-based interventions may help reduce APOC3 levels, contributing to cardiovascular health improvements, reduced atherosclerosis, and lower heart disease risk." (PMID 39684468, 2024). "When fed a high-fat diet, APOC3 deficiency was observed to be more conducive to the maintenance of plasma TG, total cholesterol, and low-density lipoprotein cholesterol levels, and the inhibition of the inflammatory response and the protection against atherosclerosis in rabbits." (PMID 34922545, 2021). "This raises the possibility that a reduction in ApoC3 will slow atherosclerosis progression and prevent vascular ischemia." (PMID 40981413, 2025). "CETP and APOC3 inhibitors represent promising therapeutictargets in the management of hyperlipidemia and atherosclerosis." (PMID 39228495, 2024). "Excessive alcohol intake significantly impacts atherosclerosis management, and a notable correlation exists between alcohol consumption and increased APOC3 levels." (PMID 39684468, 2024). "Increased circulating levels of apolipoprotein C3 (APOC3) predict cardiovascular disease (CVD) risk in humans, and APOC3 promotes atherosclerosis in mouse models." (PMID 37972731, 2024). "We have previously demonstrated that APOC3 plays an important role in type 1 diabetes–accelerated atherosclerosis." (PMID 38743496, 2024).